METTL14 (methyltransferase 14, N6-adenosine-methyltransferase non-catalytic subunit)
Diseases named in the same sentence as METTL14 in open-access papers (continued):
Sharing a sentence is not in itself a finding about the gene and the disease.
cancer (continued). "Interestingly, METTL14 also plays dual roles in various cancers." (PMID 37437245, 2023). "According to reports, the m6A “writer” proteins methyltransferase-like 3 (METTL3) and METTL14, as well as the “eraser” protein obesity-associated protein (FTO), are intricately involved in the modulation of m6A methylation and the development of various cancer types." (PMID 37938417, 2023). "Furthermore, the localization of WTAP in nuclear speckles and the formation of a complex with METTL3 and METTL14 need to be further investigated, since this knowledge may be useful for understanding the role of m6A modification in cancer biology." (PMID 36207306, 2022). "Consequently, these data suggest that METTL3 and METTL14 may serve as potential therapeutic targets and facilitate the development of new strategies to sensitize cancer cells to DNA-damaging agents in HCC." (PMID 35223847, 2022). "Thus, we suggest that among all the m6A regulators, METTL3 and METTL14 could be potential prognostic markers in cancers." (PMID 36347025, 2022). "Moreover, METTL3 and METTL14 show completely contrary effects on cancer progression, indicating that METTL3 and METTL14 may have some biological functions that are independent of m6A modification, which deserves further study." (PMID 36347025, 2022). "However, METTL14 overexpression did not impact cancer cells overexpressing PERP with a 3′-UTR mutation." (PMID 32843065, 2020). "However, as METTL3 and METTL14 have to form a heterodimer to induce m6A methylation, it seemed to be contradictory for two components of a functional complex demonstrated definitely opposite effects on progression of cancer cells." (PMID 32111213, 2020). "METTL14 stabilizes the mRNA expression of USP48 through m6A modification, indirectly participating in this cancer inhibition." (PMID 41522342, 2026). "Deletion of METTL14 in HCC cells reduces m6A levels and miR-126 expression, resulting in enhanced migration and invasion of cancer cells." (PMID 40734692, 2025). "Second, while the study focused on the interplay between OTUD7B, METTL14, and HIF-1α, it is important to recognize that cancer progression is a multifaceted process involving intricate interactions among multiple genes and factors." (PMID 40746896, 2025). "m6A regulators include writers (METTL3, METTL14, KIAA1429, and ZC3H13), erasers (ALKBH5 and FTO) and readers (YTHDF1/2/3, IGF2BP1/2/3), which are thought to play important roles in regulating cancer progression." (PMID 40774945, 2025). "Elevated METTL3/METTL14 levels have been shown to drive the growth of several cancer types, and METTL3/METTL14 inhibitors have emerged as potential therapeutic agents." (PMID 40332203, 2025). "METTL14 inhibits the expression of transcription factors NANOG and β-catenin in CRC cells, thereby inhibiting the phenotype of CRC stem cells and hindering cancer progression." (PMID 41256854, 2025). "In advanced BCa, m6A modification regulated by methyltransferase METTL14 increases the expression of lncDBET, which activates the PPAR signaling pathway and leads to increased lipid metabolism and cancer proliferation." (PMID 39802639, 2025). "In gastric cancer, METTL14 mediates the m6A level and expression of circORC5 which can sponge miR-30c-2-3p to regulate AKT1S1 and EIF4B, hence promoting cancer progression." (PMID 39087001, 2024). "High levels of METTL3/METTL14 drive the growth of many types of adult cancer, and METTL3/METTL14 inhibitors are emerging as new anticancer agents." (PMID 38691450, 2024). "In cancer cells, m6A writer complex (METTL3/METTL14/WTAP)‐mediated modification of c‐Myc mRNA is protected from YTHDF2‐mediated degradation by MSI2 with c‐Myc overexpression." (PMID 39661414, 2024).
cancer (continued). "SRSF5 is reported to promote cancer development and progression by regulating the splicing of multiple genes, including ETS1, METTL14, Mcl-1, Cyclin L2, and CCAR1." (PMID 38263157, 2024). "In numerous cancers, there is a consistent observation of dysregulated expression of key enzymes involved in m6A modification, including "writers" (such as METTL3, METTL14, WTAP), "erasers" (like FTO, ALKBH5), and "readers" (including YTHDF1, YTHDF2, YTHDF3)." (PMID 38270643, 2024). "In cancer cells, circ0008399 interacts with WTAP to recruit WTAP/METTL3/METTL14 complex in increasing TNFAIP3 mRNA stability in an m6A-dependent manner." (PMID 38075202, 2024). "The expression of METTL14 was markedly reduced in HCC and showed a significant correlation with cancer prognosis." (PMID 37915034, 2023). "We found that KLF3 expression was generally positively correlated with m1A, m5C, and m6A-related gene expression in pan-cancer, especially in YTHDF1, NSUN3, TET2, METTL14, YTHDC2, and FMR1." (PMID 37600783, 2023). "For example, a recent study showed that the collaboration of a set of WERs of m6A (‘writer: METTL14’, ‘eraser: ALKBH5’ and ‘reader: YTHDF3’) regulates cancer growth and progression." (PMID 36300630, 2023). "METTL3, methyltransferase 14, N6-adenosine-methyltransferase complex catalytic subunit (METTL14) and YTH N6-methyladenosine RNA binding protein 1/2 (YTHDF1/2) are m6A modifiers in human NSCLC and play oncogenic roles in this cancer." (PMID 35441574, 2022). "The involvements of METTL3, METTL14, FTO, and ALKBH5 in many cancers have been investigated, and they demonstrate various roles in different cancers." (PMID 35596159, 2022). "As two major components of the m6A MTC, METTL14 and METTL3 have recently been reported to play roles in malignant tumors." (PMID 35538475, 2022). "An increasing number of studies have confirmed that m6A writers (METTL3, METTL14, KIAA1429, WTAP), erasers (FTO and ALKBH5) and readers (YTHDC1, YTHDC2, YTHDF1, YTHDF2 and HNRNPC) have distinct functions within different types of cancer cells." (PMID 35042525, 2022). "Remarkably, when comparing BlCa with NUT, we found that not only METTL14 but also METTL3, VIRMA, and ALKBH5 expression was significantly decreased in cancer tissues." (PMID 35048498, 2022). "Most m6A methyltransferases and demethylases have been intensively investigated in cancers, such as METTL3, METTL14, FTO, and ALKBH5." (PMID 35596159, 2022). "The results show that knockout METTL3 and METTL14 down-regulates the expression of SRF in cells, while in the SRF-3’-UTR mutant cancer cells, the deletion of METTL3 and METTL14 don’t affect the expression of SRF." (PMID 35022030, 2022). "Recently, increasing proof has attested to the involvement of METTL14, an indispensable constituent of MTC, in cancer." (PMID 34904301, 2022). "In this way, the finding in this current study further validates the cooperation of METTL14 and YTHDF2 in affecting human cancers." (PMID 36288387, 2022). "Among them, there were 12 m6A regulatory genes, including IGF2BP1, with a significantly higher expression in LUAD tissues compared with para-carcinoma tissues, while FTO, METTL14, WTAP, and ZC3H13 showed a significantly lower expression." (PMID 36249006, 2022). "M6A methyltransferase [such as METTL3, METTL14, and METTL16] participates in the progression of malignant tumors by read, write, or erase m6A on bound RNA24." (PMID 33741902, 2021). "METTL14 promotes cancer proliferation and metastasis by promoting the EMT, protein phosphorylation or stemness of cancer cells through downstream targets such as lncRNA RP11 and microRNAs, which greatly improves the distant organ metastasis ability of CRC." (PMID 34211849, 2021). "The existing reports of methyltransferases are primarily focusing on methyltransferase-like 3 (METTL3), methyltransferase-like 14 (METTL14) and KIAA1429, which play a dominant role in the regulation between m6A methylation and cancer metastasis." (PMID 34211849, 2021).
cancer (continued). "In summary, loss-of-function screens of cancer cell lines support the biological importance of several METTLs, notably METTL1, METTL3, METTL14, METTL16 and METTL17, in promoting cancer cell growth and survival." (PMID 34285249, 2021). "Both the IGF2BP family proteins, METTL14, and YTHDC2 can function in cancers through directing m6A-modified mRNAs." (PMID 33718187, 2021). "Studies have revealed that METTL14 and ALKBH5 control the expression of each other and inhibit the expression of YTHDF3, thereby blocking RNA demethylation to degrade cancer cells." (PMID 33628845, 2021). "It is reported that the m6A writer METTL14 methylated and down-regulated lncRNA XIST in cancer cells." (PMID 34395433, 2021). "Deletion of METTL14 in HCC cells reduces m6A levels and the expression of miR-126, leading to the migration and invasion of cancer cells." (PMID 34108450, 2021). "We first elucidated the expression characteristics of these regulators in a pan-cancer context: (i) Expression changes of some clusters (YTHDF family, IGF2BP family, METTL14, FTO, and ALKBH5) were consistent in selected cancers." (PMID 33718187, 2021). "METTL3, METTL14 and RBM15 expression are all upregulated in AML compared with other types of cancer." (PMID 32513173, 2020). "Our findings highlight the function and prognostic value of METTL14 in CRC and extend the understanding of the importance of RNA epigenetics in cancer biology." (PMID 32111213, 2020). "Considering the opposite effect of the two “writer” genes in various cancers or even in the same cancer type, more experimental proofs regarding to the exact role of METTL3 and METTL14 in ccRCC are in high demand in future." (PMID 32419773, 2020). "Recently, the mRNA methylation complex containing METTL3, METTL14, and WTAP has been the subject of intense study in human cancers." (PMID 33133142, 2020). "Despite many of the studies on m6A performed in AML focused on coding RNAs, the METTL3/METTL14 and METTL16 methyltransferases can also modify non-coding transcripts with relevant role in cancer, such as lncRNAs and circular RNAs (circRNA)." (PMID 31024852, 2019). "Earlier studies have revealed the critical role of m6A regulators, particularly METTL3, METTL14, FTO and ALKBH5 in driving cancer progression and metastasis." (PMID 31069256, 2019). "Notably, while loss of function in the FA pathway typically results in bone marrow failure and a cancer-prone phenotype, these effects were not clearly manifested in Mettl14 RK mutant mice, suggesting that compensatory mechanisms might mitigate the impact of Mettl14 hypomethylation in these animals." (PMID 41053315, 2025). "Additionally, STM2457, a METTL3/METTL14 inhibitor, exhibited potent antileukemic effects in preclinical AML models, highlighting the feasibility of targeting m6A writers for cancer therapy." (PMID 40565233, 2025). "METTL14 promotes the degradation of ATF5 mRNA, reduces WDR74 transcription and β - catenin nuclear translocation, thereby inhibiting GC cell stemness and slowing down cancer progression." (PMID 41256854, 2025). "METTL14 adds m6A modifications to LHPP mRNA, inhibiting its expression, which may increase GSK3b activity and reduce HIF1A activity to promote cancer cell proliferation." (PMID 39802639, 2025). "In another mechanism, METTL14 increases miR-93-5p expression and matures pri-miR-93-5p through m6A alteration to target and inhibit TXNIP, thereby inhibiting NSCLC cell apoptosis and promoting cancer development and metastasis." (PMID 41256854, 2025). "A large number of studies of m6A regulatory mechanisms have investigated classical m6A regulators, such as METTL3, METTL14, WTAP, METTL16, FTO, ALKBH5, YTH family proteins, and IGF2BPs; anti-cancer target drugs targeting METTL3 and FTO have been proven to be effective against cancer." (PMID 38970366, 2024).
cancer (continued). "Therefore, targeting METTL3 alone should consider the results of the action triggered by METTL14, and the interaction between METTL14 and METTL3 is also a potential target for cancer therapy." (PMID 36226062, 2022). "m6A methylation requires multiple protein complexes in the cell to complete, including writers (METTL3, METTL14, and WTAP), erasers (ALKBH5), and readers, among which METTL3 is involved in cancer progression by regulating the expression of a variety of cancer-related genes." (PMID 36347844, 2022). "Therefore, screening for and designing more effective METTL14 protein inhibitors and activators are expected to provide new anticancer drugs, and targeted therapies in combination with other drugs may become a panacea for controlling many diseases and other forms of cancer." (PMID 35115038, 2022). "In addition to the METTL14–METTL3 complex, METTL16 has been discovered more recently, and its regulatory role in cancer has attracted some discussion." (PMID 36226062, 2022). "Besides that, HNRNPA2B1, YTHDC1, METTL14, WTAP, and ZC3H13 were downregulated in cancer tissues, whereas VIRMA had opposite alterations between these two databases." (PMID 33225598, 2021). "Unfortunately, selective METTL3/METTL14 inhibitors for cancer therapies are not yet available, but bisubstrate inhibitors are promising small-molecules in that they can be developed to be effective METTL3/METTL14 targeting agents." (PMID 34526985, 2021). "METTL3, METTL14 and WTAP are the main partners of “writers” belonging to m6A modulators, of which METTL3 is the primary catalytic subunit and has proved essential in promoting metastasis in several cancers." (PMID 33563300, 2021). "In addition, METTL14 is regulated by the oncogenic lncRNA LNC942 to facilitate cell growth and cancer progression." (PMID 35004679, 2021). "The role of METTL14 and IGF2BP3 in human cancers was studied before." (PMID 33718187, 2021). "In addition, other enrolled in cox formula m6A-related genes METTL14, YTHDF2, ALKBH5 played an oncogenic role in various cancers in a m6A- dependent manner." (PMID 32526707, 2020). "Compared with the control group, expression levels of HNRNPC, YTHDF1, KIAA1429, RBM15, YTHDF2, and METTL3 in cancer group were significantly up-regulated (P < 0.05), while expression levels of FTO, ZC3H13, METTL14, YTHDC1, and WTAP in cancer group were significantly down-regulated (P < 0.05)." (PMID 33193582, 2020). "Collectively, we identified a ‘METTL14-YTHDF2-lncRNA’ regulating axis in CRC cells, which presented a systemic vision of the function and mechanism of m6A in CRC and revealed a novel dimension of cancer biology." (PMID 32111213, 2020). "AML is one of the cancers with the highest expression of both METTL3 and METTL14." (PMID 31024852, 2019). "Interestingly, although WTAP, METTL3, and METTL14 are core components of the same m6A methyltransferase complex, they do not necessarily exert identical biological effects across cancers." (PMID 41301778, 2025). "The Cancer Genome Atlas (TCGA), Cancer Cell Line Encyclopedia (CCLE), and Sequence-based RNA Adenosine Methylation Site Predictor (SRAMP) databases were used to evaluate the expression of OTUD7B in ESCC and its correlation with methyltransferase-like 14 (METTL14) and HIF-1α." (PMID 40746896, 2025). "The m6A-dependent modification is reversible and regulated by methyltransferases (METTL3, METTL14, and WTAP), demethylases (FTO and ALKBH5), and m6A-binding proteins (such as YTH domain family proteins and IGF2BP family proteins), which are essential for cancer initiation and progression." (PMID 37580808, 2023). "Therefore, the situation that METTL3-mediated RNA modification and METTL14-mediated RNA modification played an opposite role in the expression of PTEN and cancer progress could be explained." (PMID 36866236, 2023). "However, METTL14, another m6A writer, was inversely correlated with TSs in most cancer types, which is not Consistent with the suggestion above." (PMID 36239411, 2023).
cancer (continued). "More importantly, we found that METTL14 showed a negative correlation with naïve B cells, macrophages M1, and resting mast cells and a positive correlation with macrophages M0 (p < 0.05), and these immune cells are closely related to cancer development." (PMID 35487915, 2022). "Previous studies have shown that METTL14 might have various functions that have not been fully identified yet, thus its role in cancer remained controversial." (PMID 36347025, 2022). "To date, the molecular mechanism of METTL14 in various malignant tumors has not been fully studied." (PMID 35115038, 2022). "RNA methyltransferases (such as METTL14, METTL3 and TAP), the demethylases(such as ALKBH5 and FTO), and the binding proteins (such as YTHDF2 and YTHDF1) are often upregulated in a variety of human cancer types to increase the expression of oncogenes and oncoproteins." (PMID 33136551, 2020). "Furthermore, Kaplan-Meier, meta-analysis and univariate Cox assay showed that the expression of m6A members including METTL3, METTL14, WTAP and FTO but not their gene mutation and amplification, was tightly associated with cancer progression and poor survival." (PMID 30953473, 2019). "Notably, AML is one of the cancers with the highest levels of both METTL3 and METTL14 expression (data from the Cancer Genome Atlas, TCGA) and, more importantly, METTL3 and METTL14 were found overexpressed in AML cells compared to normal haematopoietic progenitors." (PMID 30096915, 2018). "A previous study also showed that in human cancer, METTL3 could directly regulate the specific mRNA translation by recruiting eIF3 without coordinating with METTL14 and WTAP." (PMID 36371254, 2022). "Unlike METTL14, METTL3 had been considered as a cancer-promoting gene in various types of cancer." (PMID 34476213, 2021).